RELA (RELA proto-oncogene, NF-kB subunit)
Diseases named in the same sentence as RELA in open-access papers (continued):
Sharing a sentence is not in itself a finding about the gene and the disease.
breast cancer (continued). "However, ING4 overexpressing cells contained measurably less p-p65/RelA (Ser536) in both cytosolic and nuclear fractions (2- to 5-fold), indicating that phosphorylation of p65/RelA at the amino acid residue serine 536 was inhibited by ING4 overexpression in T47D and MCF7 breast cancer cells." (PMID 23056468, 2012). "In contrast to miR-7 expression, the relative expression levels of XIST, RELA, CD44, slug, and ESA were significantly higher in breast cancer tissues than in adjacent noncancerous tissues (p = 0.0486, p = 0.038, p = 0.0297, p = 0.0420, and p = 0.0434, respectively)." (PMID 32143670, 2020).
glioma (39 papers, 2010 to 2025). A benign or malignant brain and spinal cord tumor that arises from glial cells (astrocytes, oligodendrocytes, ependymal cells). "Side-view images of 3-D collagen invasion matrices and quantification of invading cells demonstrated that loss of either RelA or RelB each resulted in a significant decrease of glioma invasive potential." (PMID 25622756, 2015). "RELA is highly expressed in gliomas covering various datasets, including different histologies and GBM." (PMID 36116131, 2022). "LncRNA PDIA3P1 promoted glioma mesenchymal transition by competitively binding to miR-124-3p in a hypoxic environment to regulate RELA expression and activate the downstream NF-κB pathway." (PMID 34178684, 2021). "Suggesting that miR-124-3p interacts with RELA and inhibited glioma MES transition through impeding its activity." (PMID 32127518, 2020). "In summary, we revealed that hypoxia-induced factor 1 directly bound to the promotor region and upregulated the expression of PDIA3P1, which promotes cell migration and invasion through the PDIA3P1-miR-124-3p-RELA axis in human gliomas." (PMID 32127518, 2020). "Significant reduction in the migration, invasion as well as colony forming capacity of the U87MG glioma cells was observed on siRNA-mediated knockdown of NFкB (RelA)." (PMID 31992226, 2020). "In order to find its correlation with C11orf95-RELA fusion in other types of gliomas, we selected all the L1CAM IHC highly positive cases to do the FISH test using RELA break-apart probes." (PMID 32509846, 2020). "In contrast to RelA, RelB protein levels were more varied in the different glioma lines, and high RelB-expressing cells (U87, BT25, and BT116) invaded much more efficiently than low RelB-expressing cells (BT132, BT114 and U373)." (PMID 25622756, 2015). "Specific cancer pathways that were highly enriched for by our RelA targets include chronic myeloid leukemia, glioma, small cell lung cancer, pancreatic cancer." (PMID 21738489, 2011). "NF-κB signals have been shown to be elevated in glioma, and targeting RelA in glioma has been shown to decrease cell growth." (PMID 20186265, 2010). "The dysregulation of numerous signaling pathways or growth factors and the triggering of a pro-inflammatory microenvironment in gliomas may lead to the activation of NF-κB p65 (RelA)." (PMID 37892820, 2023). "The significant RELA transcriptional expression was characterised in different glioma datasets." (PMID 36116131, 2022). "Procyanidin exhibited neuroprotective activity by its capacity to regulate the secretion of S100 via the regulation of SIRT1 and the suppression of TNF-γ, NF-kB p65 (RelA subunit of NF-κB family of transcription factors) and B-cell lymphoma 2 (Bcl-2) on glioma cells." (PMID 34045956, 2021). "IGF2BP3 promotes glioma cell migration by enhancing the translation of RELA/p65." (PMID 34212046, 2021). "In addition, a positive correlation between the expression of PDIA3P1 and RELA was confirmed in glioma samples." (PMID 32127518, 2020). "In addition to glioma, positive correlation between NFкB (RelA) and FAT1 expression was also observed in other tumors like pancreatic, hepatocellular, lung and stomach cancers (data extracted from TCGA tumor data)." (PMID 31992226, 2020). "In conclusion, PDIA3P1 is a crucial link between hypoxia and glioma MES transition through the PDIA3P1-miR-124-3p-RELA axis, which may serve as a prognostic indicator and potential therapeutic target for glioma treatment." (PMID 32127518, 2020). "Consequently, the PDIA3P1-miR-124-3p-RELA axis is a possible target for glioma therapy." (PMID 34178684, 2021). "In glioma cells that display elevated noncanonical NF-κB signaling, loss of RelB attenuates invasion without affecting RelA expression or phosphorylation and RelB is sufficient to promote invasion in the absence of RelA." (PMID 25622756, 2015).
glioma (continued). "Mechanically, PDIA3P1 sponges miR-124-3p to upregulate RELA expression and, in turn, activates the downstream NF-κB pathway, which promotes a highly invasive mesenchymal (MES) transition of glioma cells." (PMID 33995499, 2021). "This occurred by sponging of miR-124-3p to modulate the expression of RELA, and activating the downstream NF-κB pathway to promote MES transition in glioma cells." (PMID 32127518, 2020). "Further studies revealed that PDIA3P1 functions as a ceRNA, sponging miR-124-3p to modulate RELA expression and activate the downstream NF-κB pathway, thus promoting the MES transition of glioma cells." (PMID 32127518, 2020). "As expected, RELA knockdown significantly inhibited NF-κB activity and the downstream protein levels of MES markers in glioma cells." (PMID 32127518, 2020). "For example, coimmunoprecipitation experiments in a glioma cell line indicated a physical interaction to occur between ING4 and RelA, the large subunit of NF-κB." (PMID 31752342, 2019). "We also evaluated PPARα, RelA, PKM1/2 and hnRNPs protein expression by Immunohistochemical (IHC) staining in a nude mouse glioma xenograft model to study the correlation among them." (PMID 26172294, 2015). "At this concentration, TWEAK failed to induce significant IκBα degradation and nuclear translocation of RelA, suggesting minimal TWEAK-induced activation of the canonical NF-κB pathway in glioma cells." (PMID 25622756, 2015). "IMP3 has been found to promote cell migration in glioma by increasing the levels of p65 protein (RELA; subunit of NF-κB heterodimer), but without modifying transcript levels." (PMID 34997006, 2022). "Moreover, NF-kappaB p65 upregulated the expression of miR-30a-5p via interaction of NF-kappaB RelA subunit and the miR-30a-5p promoter region, leading to inhibition of WWP1 and promoting glioma malignant phenotype." (PMID 34226507, 2021). "Our findings verified that RELA is a direct target of miR-124-3p, suggesting that PDIA3P1 might induce glioma MES transition by activating the NF-κB pathway." (PMID 32127518, 2020). "It is believed, based on knockdown and overexpression experiments in gliomas, that ING4 interacts with the NF-κB complex by binding to RelA, leading to the downregulation of NF-κB target genes, which reinforces the idea that ING4 shows characteristics of a tumor suppressor." (PMID 31752342, 2019). "RelB can promote invasion in glioma cells without affecting the activity of RelA and the classical NF-κB signaling." (PMID 30473630, 2018). "Specifically, we demonstrate that RelB promotes glioma invasion in the absence of RelA, and that TWEAK preferentially regulates noncanonical NF-κB signaling in glioma through a novel, signal-specific induction of NIK expression." (PMID 25622756, 2015). "CBD also facilitates the DNA binding of the glioma cell NF-κB subunit RELA, while preventing the phosphorylation of RELA on Serine-311 through the downregulation of protein kinase C ζ (PKCζ), with the sustained DNA binding of non-phosphorylated Serine-311 RELA mediating GSC cytotoxicity." (PMID 38987805, 2024).
lung carcinoma (39 papers, 2005 to 2026). "Of note, this pathogenic role of canonical NF-κB was confirmed in patients with lung cancer, in which RelA activation in lung myeloid cells is associated with poor survival." (PMID 33572260, 2021). "Multiple RNA-seq experiments were carried out to compare the transcriptomes of vector control and RelA/p65KD human A549 and H1437 lung cancer cells grown as tumour xenografts to identify differentially expressed transcripts associated with RelA/p65KD." (PMID 34503110, 2021). "Similarly, the higher expression level of RELA was proved to associate with the poor survival of patients with lung cancer." (PMID 33506873, 2021). "For example, ciRS‐7 promotes lung cancer progression through the miR‐7/RELA signaling pathway, while other studies have shown that ciRS‐7 also drives carcinogenesis via the miR‐219a/SOX5 axis in the same cancer type." (PMID 41541658, 2026). "Within the dataset n = 130 instances of lung cancer with elevated RELA expression corresponded to similarly heightened EAAT3 expression." (PMID 39987248, 2025). "To delineate the clinical relevance of our finding, we examined the levels of ALDH1B1 or the levels of nuclear RelA in primary tumor tissues from lung cancer patients." (PMID 41390768, 2025). "(2020) found that MTA2 negatively regulates NF-κB through forming the MTA2/NuRD corepressor complex and interacting with RelA to inhibit lung cancer growth and inflammation." (PMID 41159000, 2025). "Genetic deletion of RelA in lung precancerous and cancerous cells or TAMs substantially, although incompletely, blocks lung tumorigenesis in mouse models of lung cancer." (PMID 38385745, 2024). "This is also different from the tumor-promoting and -suppressive roles of intrinsic RelA and NF-κB1 in lung cancer, respectively." (PMID 38385745, 2024). "In the present study, the survival analysis revealed that the major hubs including ESR1 and RELA were verified prognostic value on the overall survival of lung cancer." (PMID 33506873, 2021). "Collectively, these data support our RelA/p65 gene signature in human lung cancer cells, and provides a mechanism by which canonical NF-κB signalling contributes to NSCLC development and progression." (PMID 34503110, 2021). "In line with its role in promoting ubiquitination and proteasomal degradation of nuclear RelA and STAT321–23, PDLIM2 deletion increased while its expression decreased nuclear RelA and STAT3, a hallmark of NF-κB and STAT3 activation, in lung cancer cells." (PMID 31757943, 2019). "In further support, blockage of RelA activation by another NF-κB inhibitor IκBα also overcame the paclitaxel resistance of lung cancer cells." (PMID 31757943, 2019). "Myeloid cell RelA is necessary to link smoke-induced inflammation with lung cancer growth and functions in the activation of Wnt/β-catenin signalling in murine and human tumour cells." (PMID 29983639, 2018). "In lung cancer, NF-κB RELA is known to be required for K-Ras-induced lung tumorigenesis, while lung tumors with RELA deletion show increased apoptosis accompanied by reduced spread and a lower grade." (PMID 29673141, 2018). "We therefore decided to examine human IEN lesions and lung carcinomas for the presence and localization of the p65/RELA subunit of NF-κB." (PMID 16332260, 2005). "Interestingly, we very recently also observed an expression of RELA in lung cancer stem cell-like cells (LCSC-like cells), which can be stimulated by applying TNF-α." (PMID 36879191, 2023). "For instance, EGR1, JUN, PPARG, and RELA may have a beneficial effect in lung cancer, related to inhibition of tumor proliferation and metastasis, induction of apoptosis, and sensitization for chemotherapeutic drugs." (PMID 36969247, 2023). "NUAK1 may activate the canonical NF-κB pathway via phospho-RelA in the lung cancer cell line A54972." (PMID 35194062, 2022). "Additionally, RELA can also promote lung cancer proliferation by regulating Wnt/β-catenin signalling." (PMID 35410586, 2022).
lung carcinoma (continued). "In both the urethane- and the oncogene-induced mouse lung cancer models suppression of canonical NF-κB using an IκBαSR super-repressor or by ablation of RelA/p65 lead to impairment of tumour growth and spread in conjunction with the accumulation of apoptotic cells." (PMID 34503110, 2021). "Accordingly, we speculated that the mechanisms of ADI on treating lung cancer were associated with the regulation of ESR1, NCOA1, RXRA, and RELA." (PMID 33506873, 2021). "In addition, SOCS3, A20 (TNFIAP3), and CYLD, the transcriptional targets of STAT3 and RelA, were increased in the lung macrophages of mice with lung cancers." (PMID 33539325, 2021). "We then examined whether PDLIM2 suppresses lung cancer through repressing the transcription factors NF-κB RelA and/or STAT3." (PMID 31757943, 2019). "Overall, our data demonstrate PDLIM2 epigenetic repression and RelA/STAT3 regulation of MHC-I, MDR1 and cancer-related genes as a previously unknown mechanism underlying lung cancer development and resistance to PD-1 blockade and chemotherapy." (PMID 31757943, 2019). "RelA functions importantly in K-Ras-induced lung cancer transformation." (PMID 29983639, 2018). "GA inhibits LPS-induced NF-κB signaling by inhibiting RelA acetylation in A549 lung cancer cells." (PMID 24723997, 2014). "It is worth considering and testing whether simultaneously targeting myeloid NF-κB2 and RelA, and perhaps also tumor RelA, shows better efficacy, since lung cancer suppression by myeloid RelA and NF-κB2 deletions involves different mechanisms, whereas intrinsic RelA promotes lung cancer as well." (PMID 38385745, 2024). "Myeloid RelA also promotes lung cancer and may be targeted for lung cancer treatment as well." (PMID 38385745, 2024). "Lin HC’s research showed that RELA attenuation significantly inhibited the proliferation and induced apoptosis of NSCLC cells in vitro, suggesting the indispensable role it has in lung cancer." (PMID 37770919, 2023). "In particular, overexpression of RELA is mainly found in ovarian cancer or cancer of the adrenal glands, whereas overexpression of c-REL is mainly found in lung cancer." (PMID 36879191, 2023). "Consistently, RelA or STAT3 co-deletion or knockdown decreased growth gene expression and lung cancer cell growth." (PMID 31757943, 2019). "In this regard, the canonical NF-κB pathway appeared as the most relevant, where nuclear RelA/p65 levels were severely and significantly reduced by CIGB-300 in all the analyzed lung cancer cell lines." (PMID 28373828, 2017). "Different from the well-studied canonical NF-κB member RelA, the role of the noncanonical NF-κB member NF-κB2 in solid tumors, and lung cancer in particular, is poorly understood." (PMID 38385745, 2024). "In this regard, we have demonstrated that through promoting the ubiquitination and proteasomal degradation of nuclear STAT3 and RelA, the PDZ-LIM domain–containing protein PDLIM2 functions as a tumor suppressor particularly important for lung cancer suppression." (PMID 33539325, 2021). "A study showed that JQ1 could disrupt the interactions between BRD4 and the acetylated lysine-310 residue on RelA, and inhibit the activation of TNF-α-mediated inflammatory cytokines in human lung cancer cells." (PMID 32303673, 2020). "Based on the findings above, we hypothesized that through restoring PDLIM2 expression to repress RelA and STAT3 activation, epigenetic drugs render lung cancer vulnerable to chemotherapeutic drugs and anti-PD-1." (PMID 31757943, 2019).
lung carcinoma (continued). "For instance, RELA is most dominantly overexpressed in ovarian cancer and cancer of adrenal glands in comparison to RELB and c-REL, while the overexpression of c-REL is most abundantly found in lung cancers, compared to that of the other subunits." (PMID 29673141, 2018). "AKT has been shown to activate a major subunit of NF-κB, RelA, thus we examined whether inhibition of AKT activation affects NF-κB expression in lung cancer cells." (PMID 29234489, 2017). "However, targeting myeloid NF-κB2 should be a much better approach, because the lung cancer suppression induced by myeloid RelA deletion is not effective as that seen in NF-κB2–KO mice in the same urethane model." (PMID 38385745, 2024). "This study proved for the first time that the exosomes secreted by lung cancer cell line H1299 could significantly change the expression of apoptosis related proteins MAP2K1, TUBA1C, RELA, and CASP6, thus promoting apoptosis of human astrocyte line SVG P12 cells." (PMID 36859173, 2023). "Moreover, inhibition of NF-κB activity either through targeting RELA with shRNAs or treatment with inhibitor did not result in lung cancer cell senescence, suggesting that NF-κB pathway is not involved in this process." (PMID 30971692, 2019). "Lung cancer cells lacking RelA are prone to undergo apoptosis." (PMID 29983639, 2018). "In fact, we found that in lung cancer over expression of BCL2 could be explained by the under expression of MIR15A, MIR16-1, and MIR16-2, while in kidney tumours over expression of DFFB, HTATIP and RELA could be related to the under expression of MIR124A-1, MIR124A-2, and MIR124A-3." (PMID 19402918, 2009). "Data from Gene Expression Profiling Interactive Analysis (GEPIA) 25 analysis confirmed a significantly positive correlation of MARCKS expression with TNFR, RELA, BCL2A1, CXCL1, RELB or TNF-alpha in lung cancer samples but not in normal lung tissues." (PMID 33754052, 2021). "Interestingly, deletion of STAT3, but not RelA, increased MHC-I expression in lung cancer cells, indicating a specific role for STAT3." (PMID 31757943, 2019).